COPZ1 (coat protein complex I subunit zeta 1)
Diseases named in the same sentence as COPZ1 in open-access papers (continued):
Sharing a sentence is not in itself a finding about the gene and the disease.
tumor (continued). "Based on the fact that COPZ1 has a high expression in tumor tissue, it is worth to further exploring the relationship of COPZ1 with the metastasis in pan-cancer." (PMID 37107648, 2023). "Our research revealed a relationship between COPZ1 expression and the tumor immune micro-environment, stemness score, and hypoxia score." (PMID 37107648, 2023). "Based on the analysis of existing data, the overexpression of coatomer protein complex subunit zeta 1 (COPZ1) is related to the increase in tumor grade and poor prognosis of GBM patients." (PMID 36710875, 2022). "Stable expression of a COPZ1 shRNA construct in U87MG inhibited tumor growth in vivo by ~60% relative to controls at day 21 after implantation (P < 0.001)." (PMID 33420375, 2021). "Inhibition of COPZ1 using RNA interference inhibited tumour growth and enhanced survival in mice by increasing intracellular iron by enhancing ferritinophagy." (PMID 34099897, 2021). "Previously we showed the mechanism of selective sensitivity of tumor cells to the inhibition of the ζ-subunit of the COPI complex, encoded by two homologous genes, COPZ1 and COPZ2." (PMID 28223711, 2017). "It has been shown that tumor cells become dependent on COPZ1, as a result of a tumor-specific downregulation of its isoform COPZ2." (PMID 26431489, 2015). "The expression of genes PTEN (tumor-suppressor), COPZ1 (involved in autophagy and protein trafficking), and GPR84 (G-protein coupled receptor) were not significantly altered due to vector integrations." (PMID 26052523, 2014). "Several reports documented tumor dependency on COPZ1 overexpression." (PMID 40978486, 2025). "In order to corroborate the validity of COPZ1 as tumor target, further efforts should also be dedicated to assess if the effects of COPZ1 inhibition are context-specific or shared by different tumor type models, as well as to validate COPZ2 as a biomarker for patient stratification." (PMID 40978486, 2025). "Such “non-oncogene addiction” may involve either physiological- or over-expression of COPZ1 gene and represent an example of tumor proteostasis dependency." (PMID 40978486, 2025). "Other studies have investigated the role of COPZ1 in different individual tumor types." (PMID 40978486, 2025). "We believe that the increasing number of tumor types addicted to COPZ1, together with the possibility that COPZ1 targeting may evoke an antitumor immune response, further support the importance and need of identifying specific COPZ1 inhibitors." (PMID 40978486, 2025). "Furthermore, the CNV level of COPZ1 in the tumor tissue and the comparable normal tissue differs noticeably." (PMID 37107648, 2023). "Our heatmap showed that in most cancers, the pro-metastasis and inhibitory markers were both positively or negatively correlated with the COPZ1 expression, which may suggest the vague role of COPZ1 in the tumor metastasis." (PMID 37107648, 2023). "We discovered that knockout of COPZ1 could significantly inhibit tumor cell proliferation in the majority of cancer cell lines derived from BLCA, BRCA, HNSC, LIHC and LUAC." (PMID 37107648, 2023). "Besides, the CRISPR Achilles’ knockout analysis revealed that COPZ1 was vital for many tumor cells’ survival." (PMID 37107648, 2023). "The correlation between COPZ1 and stem cancer may be one of the reasons why COPZ1 can maintain the survival of tumor cells." (PMID 37107648, 2023). "In addition, concerning the close relationship between hypoxia and the tumor immune microenvironment, the role of COPZ1 in tumor immune micro-environment needs further investigation." (PMID 37107648, 2023). "We further investigated COPZ1’s role in the tumor microenvironment (TME), as well as its relationship to the immunological score, stromal score, immune cell infiltration percentage, cytokines level, immune activator genes expression, and immune inhibitor genes expression." (PMID 37107648, 2023).
tumor (continued). "Herein, the data from CRISPR Achilles’ project in CCLE confirmed that knockout of COPZ1 could suppress tumor cell viability in most cancer cell lines." (PMID 37107648, 2023). "COPZ1 depletion has also been shown to induce lethal autophagy in tumor cells." (PMID 33420375, 2021). "Immunohistochemical (IHC) staining performed on 60 paraffin-embedded clinical samples, including grade II (n = 18), grade III (n = 18), grade IV (n = 18) and non-neoplastic brain tissue samples (n = 6), confirmed the result that COPZ1 increased with increasing tumor grade." (PMID 33420375, 2021). "Interestingly, the same authors found that COPZ1 vulnerability of tumor cells relies on the downregulation of the isoform COPZ2, whose gene hosts the well-known oncosuppressor miRNA152." (PMID 31947935, 2020). "In addition, local treatment with siRNA oligos targeting COPZ1 reduces tumor growth of TC xenograft models." (PMID 31947935, 2020). "Shtutman at al. attributed to COPZ1 an essential role in different tumor types (i.e., prostate, breast, and ovarian carcinoma), indeed demonstrating that depletion induces Golgi apparatus collapse, autophagy inhibition, and apoptotic cell death in proliferating and dormant cells." (PMID 31947935, 2020). "COPZ1 protein expression was slightly increased in all the tumor cell lines, and greater in 8505C." (PMID 26431489, 2015). "This raises the possibility that other mechanisms, in addition to COPZ2 downregulation, may be involved in determining tumor cell COPZ1 dependency." (PMID 26431489, 2015). "In addition to a direct effect on tumor growth, COPZ1 targeting may have potent immune-stimulatory effects through the establishment of a systemic inflammatory response, thus turning “cold” immunosuppressive tumors into “hot” inflamed tumors." (PMID 40978486, 2025). "Also, in LUAD COPZ1 depletion leads to in vitro and in vivo growth reduction of tumor cells." (PMID 40978486, 2025). "However, the COPZ1 expression was low in tumor tissue in the LAML and PADC." (PMID 37107648, 2023). "Collectively, our findings support the notion that targeting COPZ1 may represent a promising therapeutic approach for TC, considering its specificity for cancer cells, the lack of effect on normal cells, and the capacity to prompt an anti-tumor immune response." (PMID 40978486, 2025). "These 6 tumor-exclusive proteins detected in every single sample comprised MARCKSL1, IKBIP, COPZ1, TIMP1, FAM50A and DPM3." (PMID 39681068, 2024). "Contrary to the depletion of COPZ1, where COPZ2 expression protects normal cells from Golgi disruption, depletion of ARCN1 disrupted the Golgi equally in normal and tumor cells." (PMID 28223711, 2017). "The evidence that COPZ1 knockdown kills both proliferating and non-dividing tumor cells, but spares normal cells, suggested the potential of COPZ1-targeting therapies to selectively eradicate cancer cells, independently of their proliferative status." (PMID 40978486, 2025). "In fact, COPZ1 depletion activates a type I IFN response, which boosts a pro-inflammatory form of cell death able to promote dendritic cell maturation and subsequent activation of a T cell cytotoxic activity against parental tumor cells." (PMID 40978486, 2025). "Despite the numerous studies proposing COPZ1 as a possible target for different tumor types, COPZ1 inhibitors are not yet available." (PMID 40978486, 2025). "Finally, we verified the expression of COPZ1 in HCC cells, and proved its ability of sustaining tumor growth and invasion with biological experiments." (PMID 37107648, 2023). "The results demonstrated that tumor tissue had much greater levels of COPZ1 expression than normal tissue in DLBC, GBM, THYM, OV, TGCT, LGG and SKCM, but lower in tumor tissue in LAML." (PMID 37107648, 2023). "Inhibition of COPZ1 kills a majority of tumor cell lines, while not affecting the growth of normal cells." (PMID 28223711, 2017).
tumor (continued). "The dependency upon Cyclin D1, MASTL and COPZ1 activity is restricted to tumor cells and not normal thyroid cells, as previously reported for other tumor types." (PMID 26431489, 2015). "The relationship between COPZ1 and tumor stemness has not been investigated before." (PMID 37107648, 2023). "However, whether COPZ1 inhibition can sensitize the anti-tumor effect of immune checkpoint inhibitors has not been reported, which is a promising direction for further exploration." (PMID 37107648, 2023). "Interestingly, COPZ1 knockdown kills both proliferating and non-dividing tumor cells, but does not affect normal cells, thus suggesting that COPZ1-targeting therapies have the potential for eradicating cancer cells, independently of whether they are actively proliferating." (PMID 26431489, 2015).
cancer (7 papers, 2012 to 2025). A tumor composed of atypical neoplastic, often pleomorphic cells that invade other tissues. "A pan-cancer bioinformatic analysis showed that high expression of COPZ1 was linked to poor overall survival in many cancers." (PMID 40978486, 2025). "We found that COPZ1 was extremely prevalent in a variety of cancer types, and high expression of COPZ1 was linked to poor overall survival in many cancers, while low expression in LAML and PADC was correlated with tumorigenesis." (PMID 37107648, 2023). "With the mRNAsi (mRNA expression-based stemness index) of six types of cancers acquired from a published article, in both of the six different types of tumors, we observed that COPZ1 was highly associated with the mRNAsi score." (PMID 37107648, 2023). "We subsequently assessed the association between the representation of the COPZ1 gene and those differential DNA-methylated CpG sites in six types of cancer." (PMID 37107648, 2023). "Depletion of COPZ1 can lead to loss of cancer-specific COPI function and subsequent paralysis of the Golgi apparatus." (PMID 32537629, 2020). "Recent research has discovered an antibody conjugated polymer nanogel system called Nano-ERASER, which could degrade COPZ1 in cancer cells and finally cause cancer cell death." (PMID 37107648, 2023). "Additionally, in both of the six cancer types, reduced expression of COPZ1 was substantially linked to a higher stromal score." (PMID 37107648, 2023). "We are aware that this review is not fully exhaustive; due to space limitation, the original articles documenting cancer dependency on COPZ1 and COPI have been briefly illustrated." (PMID 40978486, 2025). "In this review we summarize the role of the coatomer complex I (COPI) in cancer, with specific interest to the COPZ1 subunit." (PMID 40978486, 2025). "The sixth gene (COPZ1) turned out to play an important role in coping with different types of cancer in mammals." (PMID 39227733, 2024). "In our research, the amount of COPZ1 was favorably correlated with the hypoxia score in many malignancies." (PMID 37107648, 2023). "We next carried out the correlation analysis between the COPZ1 expression and the expression of upregulated TFs among the six kinds of cancer." (PMID 37107648, 2023). "In our current work, we found that there was a clear link between the hypoxia score and the amount of COPZ1 in several cancers." (PMID 37107648, 2023). "In this study, we sought to explore the molecular characteristics of COPZ1 and its clinical prognostic value through a pan-cancers bioinformatic analysis." (PMID 37107648, 2023). "Taken together, Our findings can serve as support for further research into COPZ1’s function in malignancies and the possibility of COPZ1-specific cancer therapies." (PMID 37107648, 2023). "In this study, we carried out a bioinformatic analysis to explore the expression profile, molecular characteristics and clinical prognosis value of COPZ1 in pan-cancers." (PMID 37107648, 2023). "The expression profile of COPZ1 was analyzed in pan-cancer and corresponding normal tissue types through TIMER2 and GEPIA2." (PMID 37107648, 2023). "In this study, bioinformatics analysis was carried out to comprehensively explored the function and regulation mechanism of COPZ1 in pan-cancer by combining GTEx and TCGA data." (PMID 37107648, 2023). "With comprehensive consideration of the results of COPZ1 differential expression in cancer and corresponding normal tissue, and the association between COPZ1 expression and patients’ survival, we speculated whether COPZ1 was essential for those cancer cells’ survival." (PMID 37107648, 2023). "The COPZ1 expression in the rest cancers was also explored in the GEPIA database with GTEx normal data, and similar trends occurred in TIMER also observed in the GEPIA." (PMID 37107648, 2023). "According to our study’s findings and earlier re-search, COPZ1 appears to be a promising therapeutic target for the treatment of cancer." (PMID 37107648, 2023).
cancer (continued). "The most difference between them is their expression pattern: COPZ1 expresses in most cancer cells and normal cells, while COPZ2 expresses in the normal cells and is down-regulated in cancer cells." (PMID 37107648, 2023). "The further analysis showed that COPZ1 expression had a positive correlation with the M2 infiltration in most cancer types." (PMID 37107648, 2023). "To look into possible regulatory mechanisms of high COPZ1 expression in cancer, we carried out analysis from many aspects, including epigenetics, genomics, transcription factors and microRNA." (PMID 37107648, 2023). "Oliver's study elucidates the mechanism by which cancer cells emit apoptosis signals when COPZ1 is depleted." (PMID 32537629, 2020). "The possible effect of COPZ1 inhibition by MCFA-F3 in cancer cells remains to be investigated." (PMID 40978486, 2025). "Another issue deserving further investigation is the possible integration of COPZ1 targeting with standard cancer treatment; it would be important to assess if COPZ1 targeting might enhance the sensitivity of cancer cells to conventional therapeutic agents." (PMID 40978486, 2025). "Besides, we also identified many transcription regulators and microRNAs that were positively or negatively correlated with COPZ1 expression in different cancers." (PMID 37107648, 2023). "In summary, our study is the first comprehensive analysis of COPZ1 in pan-cancers." (PMID 37107648, 2023). "Therefore, it is pointed out that the expression level of the COPZ2 gene could be decreased via silencing microRNA 152 and COPZ1-targeting agents could be deployed to selectively kill different cancer cells." (PMID 39227733, 2024). "Except for the BLCA, in the other five kinds of cancer, low expression of COPZ1 exhibited more antitumor immune cells infiltration, including B cells, neutrophils, CD8+T cells, CD4+T cells and M1 macrophages, while high expression of COPZ1 associated with more Tregs infiltration." (PMID 37107648, 2023). "However, the regulation mechanism and prognostic potential of COPZ1 in different cancers remains unclear." (PMID 37107648, 2023). "We found that COPZ1 could be a robust prognostic marker for various types of cancer." (PMID 37107648, 2023). "To investigate the connection between hypoxia and COZP1, we analyzed the correlation of COPZ1 and HIF1A as well as the LOXL2 in 33 cancer types." (PMID 37107648, 2023). "Our study provides a multi-dimensional pan-cancer analysis of COPZ and demonstrates that COPZ1 can serve as both a prospective target for the treatment of cancer and a prognostic marker for a variety of cancer types." (PMID 37107648, 2023). "Reduced expression of COPA, COPB1, COPB2, COPG1, COPD, and COPZ1 induced the punctate GFP-LC3 formation in MDA-MB-231, MDA-MB-468 and SKOV3 cancer cell lines." (PMID 22745748, 2012). "They selected COPZ1 protein for validation, and showed that Nano-ERASER specifically degraded COPZ1 leading to cancer cell death without affecting normal cells." (PMID 40978486, 2025). "However, studies on COPZ1 and EFTUD2 in HCC are still few, but some studies have shown that COPZ1 and EFTUD2 are closely related to cancer development." (PMID 32537629, 2020). "Cancer cells dependency on physiological expression level of COPZ1 gene fulfils the classical NOA definition: “dependence of cancer cells on the normal functions of genes which are not classically or inherently oncogenic per sé as not mutated and expressed at physiological levels”." (PMID 40978486, 2025). "Considering that MCFA-F3 treatment neither reduce COPZ1 protein level, nor interferes with the correct COPI complex assembly, we consider unlikely its effect in COPZ1-addicted cancer cells." (PMID 40978486, 2025).
infection (3 papers, 2021 to 2022). The state of being infected such as from the introduction of a foreign agent such as serum, vaccine, antigenic substance or organism. "Infection of previously COPZ1 silenced U87MG cells with a lentiviral construct expressing COPZ1 (OE-COPZ1) resulted in lower expression of NCOA4." (PMID 33420375, 2021).
COPZ1 also shares sentences with these, for which no sentence is quoted: acute myeloid leukemia (1 paper); colon cancer (1); diffuse large B-cell lymphoma (1); esophageal carcinoma (1); leukemia (1); lymphoid neoplasm (1); mesothelioma (1); movement disorder (1); ovarian carcinoma (1); ovarian serous cystadenocarcinoma (1); prostate carcinoma (1); skin cutaneous melanoma (1); testicular germ cell tumor (1); thymoma (1).